AR (androgen receptor)
Diseases named in the same sentence as AR in open-access papers (continued):
Sharing a sentence is not in itself a finding about the gene and the disease.
tumor (continued). "Out of 419 tumor samples, we found that 43 samples have high levels of ERα compared to AR, which represents about 10.26% of the total tumor population examined." (PMID 26575018, 2015). "KDM4A and AR are recruited to cis-regulatory elements of the AR target gene p27kip1, where they inhibit the expression of that tumor suppressor via H3K4me3 demethylation." (PMID 26397136, 2015). "Logically, most hormonal therapies target suppression of AR functions, however, despite initial success, the tumor cells acquire resistance and continue to grow again through the restoration of complex AR signaling." (PMID 26295410, 2015). "On univariate survival analysis, tumor size, tumor stage, the presence of distant metastasis, histologic grade, and the expression of DBC1 and AR were significantly associated with both overall survival (OS) and relapse-free survival (RFS)." (PMID 26249023, 2015). "Since AR is a ligand-dependent DNA-binding transcription factor that governs downstream genes to facilitate growth of normal as well as tumor prostate tissue, the role of transcriptional coactivators become critical in modulating AR functions." (PMID 26295410, 2015). "In advanced PCa, it is highly possible that a functional synergy between AR and the NF-κB escalates the resistance to therapeutic regimes and promotes aggressive tumor growth." (PMID 26295410, 2015). "To determine the prevalence of AR positivity, with emphasis on TNBCs, and to investigate AR status during tumor progression, we evaluated a large series of primary BCs and matching metastases and recurrences." (PMID 26552477, 2015). "Taken together, these data strongly suggest that AR tumors are highly enriched with tumor initiation capacity and invasive growth pattern." (PMID 26336988, 2015). "Expression of AR-FL was significantly increased in 11/14 tumours (average = 1.42-fold) in response to treatment with enzalutamide (one sided t test p = 0.004)." (PMID 26554309, 2015). "Further, AR status is highly conserved during tumor progression and a change only occurs in a small fraction (4.1 %)." (PMID 26552477, 2015). "An alternative mechanism of AR activation has also been described as cross-talk with other cellular signaling pathways leading to tumor growth and CRPC progression." (PMID 29147414, 2015). "More recent studies have highlighted the tumour promotional effects of the AR particularly in the event of estrogen disruption." (PMID 26341737, 2015). "The therapeutic targeting of driver aberration (e.g. an overactive AR) can activate adaptive survival pathways, leading to apoptosis inhibition, tumour cell plasticity, and the emergence of treatment resistance." (PMID 25896606, 2015). "Western blot analysis of biopsied tumor tissue that had been established in intact mice revealed that full-length AR remained the predominant protein species." (PMID 25908785, 2015). "In summary, we demonstrate that catalytic Topo II inhibitors can block AR signaling and inhibit tumor growth of castration-resistant xenografts, identifying catalytic Topo II inhibitors as potentially novel drugs to treat in patients with CRPC." (PMID 26009876, 2015). "Our study confirmed, that AR status is highly preserved during tumor progression, but we did identify a few samples (n = 5) with discordant AR status from the primary tumor to the lymph node metastases." (PMID 26552477, 2015). "In this cohort, the prototypical, full length AR transcript (AR-FL) was expressed at the highest average levels in Luminal A and lowest levels in Basal tumor sub-groups." (PMID 26554309, 2015). "From a biological and therapeutic point of view, the dynamics of AR status during tumor progression is an important consideration." (PMID 26552477, 2015). "The specific inhibitor of Hsp90, 17-allylamino-17-demethoxygeldanamycin (17-AAG), prevents the nuclear localization of androgen receptor in AI tumor at much lower doses than that required to inhibit androgen induced nuclear import of androgen receptors (AR)." (PMID 25973397, 2015).
tumor (continued). "AR changes during tumor progression would have important clinical implications for patient selection of anti-AR therapy." (PMID 26552477, 2015). "In the future, the optimal anti-tumour strategies will be those that target rational combinations of pathways in concert with AR, and select appropriate patient populations within which to test." (PMID 25896606, 2015). "We tested AR and CaM expression in serial sections of tumor tissues and found a strikingly a greater nuclear accumulation of CaM in tumors that had a high level of AR than in tumors with a low AR level." (PMID 25704883, 2015). "Studies with the new anti-androgen agent MDV3100 (enzalutamide) indicate one of the ways it inactivates AR nuclear activity in the tumor cells is by preventing nuclear translocation, thus retaining a significant amount of AR the cytoplasm." (PMID 25730905, 2015). "Further support for its inhibitory role in PCa comes from its inverse correlation with AR protein in primary prostate tumors and its altered pattern of expression in tumor metastases." (PMID 26325261, 2015). "AR activity is the primary source of proliferation and survival signals in PCa tumor cells, both in primary disease and in CRPC." (PMID 25871401, 2015). "Despite enormous genomic heterogeneity, this biological homogeneity means that almost all tumours will initially respond to ligand depletion of the AR." (PMID 25896606, 2015). "AR protein expression of the tumor epithelium (with highest Gleason pattern) and the surrounding stroma was quantified using the Quick score for steroid receptors." (PMID 25793207, 2015). "In the biopsy specimens, on the other hand, AR expression was significantly higher in tumor cells compared to NE." (PMID 25793207, 2015). "PCa tumor growth and NED are at opposite ends of the prostate epithelial cell spectrum of behaviors, with NED characterized by cell cycle withdrawal, loss of AR expression and acquisition of a neuronal phenotype." (PMID 25693195, 2015). "Emerging evidence demonstrates the involvement of PKD in key signaling pathways that regulate tumor cell proliferation such as β-catenin, androgen receptor, mTORC1-S6K1, and MAPK in various tumor cell models." (PMID 25747583, 2015). "The role of the androgen receptor is pivotal, and androgen receptor serine 81 mediates Pin1 interaction and defines tumor grade by modulating androgen receptor function." (PMID 26039047, 2015). "In patients with metastatic PCa, standard treatments involve either surgical or medical castration, which effectively prevents testicular testosterone from driving androgen receptor (AR) activation in the tumor cell." (PMID 25906751, 2015). "Several other authors established a link between low levels of AR in tumor stroma, PCa aggressiveness, metastasis, efficacy of castration therapy, and even survival after RP." (PMID 25793207, 2015). "Adjuvant ADT to EBRT has its synergistic effects by decreased tumor cell hypoxia, decreased DNA repair, and decreased AR mediated cell growth." (PMID 25793207, 2015). "Subsequently, AR binds at distinct genomic regions to mediate expression of directly responsive genes, ultimately leading to tumor cell proliferation." (PMID 26412853, 2015). "Since PacMetUT1 has unique features in expressing low AR and high levels of ERα, we queried the cancer genome atlas database (TCGA) to check how many tumor samples have similar expression patterns." (PMID 26575018, 2015). "Results were compared to tumor phenotype, biochemical recurrence, androgen receptor (AR) and prostate specific antigen (PSA) as well as molecular subtypes defined by ERG status and genomic deletions of 3p, 5q, 6q, and PTEN." (PMID 25825985, 2015). "It is noteworthy, that numerous AR-positive tumour cells were observed in the metastases of the Ptenpc−/−Stat3pc−/− PCa mouse models, underlining the relevance of our model to human PCa25." (PMID 26198641, 2015).
tumor (continued). "Variables included in a multivariate analysis were age, grade, tumor size, ER percent staining, and the dichotomized AR:ER ratio." (PMID 24451109, 2014). "DOC2/DAB2 and DAB2IP are considered to be tumor-suppressor genes and are able to counteract the formation and oncogenic action of the AR–Src complex by physically interacting with Src." (PMID 25184116, 2014). "Docetaxel treatment did not induce a loss of c-MYC expression (42.3%) compared to vehicle treated tumors (41.2%), which was consistent with AR expression in tumor tissues." (PMID 25072314, 2014). "Alternative means to inhibit AR function by using a decoy molecule representing AR NTD demonstrably suppress tumor growth and hormonal progression." (PMID 25520915, 2014). "The suppression of androgens by androgen deprivation therapy (ADT) alone or together with androgen receptor (AR) antagonists initially induces tumour regression and a period of cancer control, accompanied by nondetectable or exceedingly low PSA levels." (PMID 25276838, 2014). "To assess the activity of AUY922 on the attenuation of transcriptional activity in vivo, we used immunostaining to determine the expression of the c-MYC transgene, which in this tumor model is driven by AR transcription via a probasin promoter." (PMID 25072314, 2014). "Using AR + TNBC cell line and xenograft models we evaluated the effectiveness of PI3K inhibitors, used alone or in combination with an AR antagonist, on tumor cell growth and viability." (PMID 25103565, 2014). "The objective of this study was to investigate nanobubbles carrying androgen receptor (AR) siRNA and their in vitro and in vivo anti-tumor effects, when combined with ultrasonic irradiation, on androgen-independent prostate cancer (AIPC)." (PMID 24798477, 2014). "Understanding the molecular mechanisms of AR in tumor microenvironment will undoubtedly further improve the results obtained with antitumor therapeutic strategies." (PMID 24949437, 2014). "Although more studies comparing AR target gene expression in different ethnic groups have to be carried out, one can expect that differences occur in certain tumor subgroups as a consequence of dissimilar AR transcriptional activities." (PMID 24280133, 2014). "Although systemic bioavailability of both stilbenes is very low, both compounds were also able to downregulate tumor growth and AR-signalling in vivo." (PMID 24887556, 2014). "While AR- cells with flat or pseudo-diploid CNV profiles (clone B) were identified at the time of response, a new tumor lineage of AR+ cells (clone C) with CNV altered profiles was detected during relapse." (PMID 25084170, 2014). "In spite of this, androgen receptor (AR) dysregulation and its therapeutic value has only recently been investigated in this group of neoplasms." (PMID 24505496, 2014). "A new means to deplete androgens is a selective CYP17 inhibitor, which inhibits both testicular-derived androgen production and tumor-derived androgen synthesis, meaning a great advance toward durable androgen depletion and suppression of AR activity." (PMID 25520915, 2014). "The secondary endpoints include tumor response by the Response Evaluation Criteria in Solid Tumors (RECIST), AR modulation and levels of circulating tumor cells and markers of CYP17lyase inhibition." (PMID 25062956, 2014). "In order to investigate this possibility, two approaches have been taken, using the tumour ErbB2-IR together with three other tumour markers (Ki67 index, epithelial AR-IR and pAkt)." (PMID 25215939, 2014). "3-D suspension culture and in vivo PCa tumor growth restore AR through downregulation of AP-4, enhancing integrin α2 expression and adhesion to ColI which is rich in bone matrices." (PMID 25200184, 2014). "Ordinal regression analyses with tumour ErbB2-IR, AR-IR and Ki67-index as the independent variables and the tumour stage as the dependent variable." (PMID 25215939, 2014).
tumor (continued). "Further, histochemical analysis of treated MYC-CaP/CR tumor tissue for AR expression revealed that both vehicle and docetaxel treated tumors displayed strong AR nuclear staining." (PMID 25072314, 2014). "CRPC tumours sustain the expression of AR and its regulated genes, indicating that the AR signaling continues to function." (PMID 25360799, 2014). "In MCF7 xenografts (ER+/AR+) enzalutamide inhibited E2-driven tumor growth as effectively as tamoxifen by decreasing proliferation." (PMID 24451109, 2014). "Within tumours, the amount of AR plays a crucial role in determining cell growth, resistance to therapy and progression to fatal castrate recurrent PCa in which prostate cells appear to become independent of androgenic steroids." (PMID 24895212, 2014). "For advanced tumors or tumor recurring after primary surgery or radiation therapy the androgen receptor (AR) and its signaling network are the prime targets of therapy." (PMID 25338271, 2014). "Altogether, our study strongly suggests tumor stromal microenvironment induced AR activation as a direct mechanism of CRPC." (PMID 25333263, 2014). "These mice paradoxically develop poorly differentiated PCa and, most importantly, restoration of AR function in epithelial basal cells leads to tumor suppression." (PMID 24744780, 2014). "It has been proposed that higher activity of androgen pathway functions as a tumor-promoting factor in male hepatocarcinogenesis, as knockout of AR expression in hepatocytes delayed the development of N’,N’-diethylnitrosamine (DEN)-induced HCC." (PMID 25469175, 2014). "Tyrosine phosphorylation of AR has been reported; it appears to be accomplished by a number of different kinases and is important for tumor growth under androgen depleted conditions." (PMID 25277175, 2014). "In conclusion, pertinacious AR signalling is implicated in the progression to CRPC with the levels of the receptor mediating the life and death of tumours." (PMID 24895212, 2014). "It has been suggested that residual androgen production within the tumor microenvironment contributes to persistent AR signaling." (PMID 24466341, 2014). "Another study demonstrated that secretory proteins from prostate neuroendocrine cells activate NF-κB signaling in the tumor cells, which in turn transcriptionally activates AR in the tumor cells to promote castration-resistant cell growth." (PMID 25566502, 2014). "Mir let-7c has been shown have tumour suppressive potential by attenuating androgen receptor expression, through targeting its c-Myc-driven transcription." (PMID 25496077, 2014). "Yet, a few isolated tumor cell lines, especially those that have lost AR expression, readily adapt EMT phenotypes and are relatively invasive and metastatic." (PMID 25566502, 2014). "In metastatic prostate cancer (PCa), androgen deprivation therapy (ADT), constitutes the gold standard treatment to induce tumor regression by suppressing AR activation." (PMID 25084170, 2014). "Both SDF-1 and IL-6 can activate the androgen receptor (AR) at low levels of androgens in PCa cells and contribute to tumor progression to the castration resistant stage." (PMID 24664419, 2014). "The results of the in vivo tumor growth inhibition assay, qRT-PCR, and Western blot analysis also initially demonstrated the inhibitory efficacy of the nanobubbles carrying AR siRNA against C4-2 xenograft tumors." (PMID 24798477, 2014). "Recurrent patients with high AR levels had an improved recurrence-free survival if their tumor also expressed high CAMK2N1 protein levels." (PMID 25296973, 2014). "The dependence of PDEF expression on NWD1 in a variety of tumor cell lines therefore suggests another connection of NWD1 to AR signaling pathways." (PMID 24681825, 2014). "Tumor types according to Farmer were grouped as follows: HR + (AR+/-), n = 365), HR-/AR + (n = 56), and HR-/AR- (n = 101)." (PMID 25070172, 2014).
tumor (continued). "Androgen signalling plays a pivotal role in PCa and increased AR expression is a common feature of both primary tumours and metastases, with a high AR profile in the latter correlating to larger tumour size." (PMID 24895212, 2014). "It appears, therefore, that the drastic anti-tumor effects of GSK-3β inhibition cannot be solely explained by modulation of the androgen-receptor axis." (PMID 25344861, 2014). "The androgen receptor (AR) was expressed in the cytoplasm and/or the nucleus within the tumor cells; thus, the tumor appeared to exhibit apocrine features." (PMID 24520287, 2014). "Enduring expression of the androgen receptor in PCa contributes to tumour survival and proliferation as well as facilitating progression to fatal CRPC status." (PMID 24895212, 2014). "In other words, when variables are held constant, there is an influence of the combination of ErbB2-IR x AR-IR, so that the higher the scores, the higher the tumour stage number." (PMID 25215939, 2014). "We recently reported the development of a MYC-CaP castrate resistant (MYC-CaP/CR) transplant tumor model, which expresses amplified wild type AR." (PMID 25072314, 2014). "Activated AR can downregulate E-cadherin expression to promote the activation of epithelial-mesenchymal transition and tumor metastasis." (PMID 24397471, 2014). "In order to account for this, we undertook ordinal regression analyses with tumour ErbB2-IR, AR-IR and Ki67-index as the independent variables and the tumour stage as the dependent ordinal variable." (PMID 25215939, 2014). "Further, in vivo assessment of AR expression in MYC-CaP/CR tumor tissue revealed heterogeneous staining for AR within tumors treated with AUY922 as monotherapy or in combination." (PMID 25072314, 2014). "In order to analyze the effects of FIDAS and RSV on AR/ARΔLBD-signalling, experiments were performed in PC-3 cells, transiently transfected either with AR and/or Q640X, an ARΔLBD recently isolated from a metastatic castration resistant tumor." (PMID 24887556, 2014). "AR can function as a positive regulator of proliferation and stimulate the development of neoplasia which indicates a direct role of AR in promoting PC." (PMID 25309637, 2014). "Unique to AZD3514 as a pharmacological modulator is its ability to down regulate the protein both in vitro and in vivo and its anti-proliferative activity against Dunning R3327H prostate tumours in rats correlated to a reduction in AR levels in tumour tissue." (PMID 24674711, 2014). "The majority of CRPC tumours overexpress AR, and the AR gene is amplified in approximately a third of cases." (PMID 24895212, 2014). "The expression rate of AR was higher in adjacent normal kidney than in RCC tissues, and it was negatively associated with tumour stage and Fuhrman’s grade." (PMID 28326246, 2014). "By using these experimental settings, it has been shown that stromal AR modulates the release of pro-inflammatory chemokines by CAFs, thereby promoting recruitment of inflammatory and immune cells in tumor microenvironment." (PMID 25646090, 2014). "In summary, our results suggest a new mechanism for the development of EC, in which FOXA1 promotes tumor cell proliferation through AR and activates the Notch pathway by influencing AR expression." (PMID 24512546, 2014). "AR, in addition to GCDFP-15, is an effective IHC marker for identifying apocrine features and is frequently expressed in AC; in the present case, the AR was expressed in the nucleus and/or the cytoplasm of the tumor cells." (PMID 24520287, 2014). "The TRAMP transgenic mouse strain is engineered to express the SV40 virus large T and small t tumor antigens in prostate epithelial cells under the control of the AR-responsive rat probasin promoter." (PMID 23852643, 2013). "This tumor suppressive activity is consistent with AR role as the driver of differentiation in prostate epithelium." (PMID 24391862, 2013).